RNU6-1234P (RNA, U6 small nuclear 1234, pseudogene)
Gene: Small nuclear RNA gene on chromosome 14 (29,811,916 to 29,812,018, forward strand). Ensembl gene ENSG00000252686.
Homologues: Orthologues: chimpanzee U6 (100% identical), macaque U6 (96% identical), dog U6 (76% identical), guinea pig U6 (76% identical). Paralogues in human: RNU6-21P (81% identical), RNU6-549P (81% identical), RNU6-1263P (80% identical), RNU6-235P (80% identical), RNU6-574P (80% identical), RNU6-728P (80% identical), RNU6-97P (80% identical), RNU6-1029P (79% identical), RNU6-1122P (79% identical), RNU6-154P (79% identical), RNU6-25P (79% identical), RNU6-333P (79% identical), and 1291 more.